BCL2 (BCL2 apoptosis regulator)
Diseases named in the same sentence as BCL2 in open-access papers (continued):
Sharing a sentence is not in itself a finding about the gene and the disease.
breast carcinoma (continued). "In sharp contrast, Bcl2 levels remained steady or even increased along with hyperpolarization of MMP in NO treated breast cancer cells of CA origin." (PMID 27473585, 2016). "Meanwhile, inhibition of autophagy with CQ also markedly attenuated the increased Bax/Bcl-2 ratio in the two breast cancer cells." (PMID 27263652, 2016). "The ratio of the anti-apoptotic gene/pro-apoptotic gene was measured by semi-quantitative RT-PCR, and all 5-FU treated cells showed low Bcl-2/BAX ratios due to induction of apoptosis in breast cancer cells." (PMID 26716512, 2016). "Of note, silibinin-exposed breast cancer cells showed up-regulation of Bcl-2 adenovirus E1B 19-kDa-interacting protein 3 (BNIP3)." (PMID 27657126, 2016). "It has been reported that 17β-estradiol inhibits MDA-MB-231 breast cancer cell growth by increasing BAX/BCL-2 and reducing pERK1/2, while it is mostly agreed that it promotes proliferation and cell-cycle progression of MCF-7 cells." (PMID 27101408, 2016). "Another study also reported the ability of Bcl-2 to accelerate lung metastasis in a similar breast cancer model." (PMID 26621844, 2016). "PQ1 has been reported to induce apoptosis in human breast cancer cells through the upregulation of caspases and an alteration in Bax/Bcl-2 expression ratio." (PMID 26840298, 2016). "Increased pro apoptotic caspase-3 protein level and enhanced Bax/Bcl-2 ratio in the presence of genistein have also been observed in MCF-7 human breast cancer cells." (PMID 27942504, 2016). "We observed that ER or PR negativities are more frequent in patients with luminal B HER2-negative breast cancer who were older than 45 years old, had lower Bcl-2 expression, and a higher Ki 67 index." (PMID 27619909, 2016). "Another important factor involved in this process is the antiapoptotic Bcl-2, which is highly expressed in 40–80% of breast cancer patients." (PMID 26697130, 2016). "Metformin treatment reduced breast cancer cell viability, increased miR-26a expression, and led to a reduction in BCL-2, EZH2, and PTEN expression." (PMID 27517917, 2016). "InuA upregulated the expression of p21 and Bax, induced the cleavage of PARP, and reduced the expression of Cdk2, Cdk4, Cdk6, Cyclin D1, Cyclin E, c-Myc, and Bcl2 in both breast cancer cell lines." (PMID 27105525, 2016). "Apoptosis was induced in breast cancer cells by 17-DR as confirmed by the down-regulation of Mcl-1 and Bcl-2, and up-regulation of Bax protein levels." (PMID 27658586, 2016). "EGCG induced an increase in endoplasmic reticulum calcium ([Ca2+]ER) and a decrease in cytosolic Ca2+ by inhibiting Bcl-2 mediated Ca2+ leakage from the endoplasmic reticulum in MCF-7 breast cancer cells." (PMID 27483305, 2016). "In the current study, dietary treatment with PE increased Bax expression and decreased Bcl2 expression in mammary tumors induced by DMBA with a proapoptotic shift in Bax/Bcl2 ratio." (PMID 26699876, 2016). "The mammary tumor sections from DMBA control rats showed extensive expression of cytoplasmic Bcl2 protein which was only slightly altered by the low dose of PE." (PMID 26699876, 2016). "As feline mammary tumors seem to mimic the human counterpart in overexpressing BCL-2, they seem to be suitable models to test this promising therapy." (PMID 29056725, 2016). "Madewell and colleagues examined the subcellular distribution of the BCL-2 protein in a collection of feline tumors immunohistochemically, and detected its presence in all mammary tumors." (PMID 29056725, 2016). "In line with this role, the loss of H3K9me2, as seen at an oestrogen-induced enhancer in breast cancer cells, promotes reactivation of the apoptosis regulator bcl2." (PMID 26551560, 2015).
breast carcinoma (continued). "One of its chemical structures, namely, quercetin, has been reported to inhibit pancreatic and breast cancer cell growth and induce apoptosis via Bcl-2 expression downregulation and upregulation of Bax expression." (PMID 26613081, 2015). "Experiments with resveratrol in MCF-7 breast cancer cells revealed that the polyphenol acts as an estrogen receptor agonist, but, at the same time, reduces the Bcl-2/Bax ratio implying that it is a candidate for hormone replacement therapy (HRT)." (PMID 26694341, 2015). "Tamoxifen treated ER+ breast cancers often increase Bcl-2 and Bcl-xL levels, decreasing acute tumor response to Tamoxifen and increasing long-term tamoxifen resistance." (PMID 25784482, 2015). "For example, lower BCL2 expression is related with poorer clinical outcome in patients with metastatic breast carcinoma in luminal breast cancers and overexpression of the BCL2 gene is found to be associated with resistance against chemotherapeutics treatment." (PMID 26406239, 2015). "VPA treatment of MCF-7 breast cancer cells was associated with reduction of telomerase activity, increase in Bax/bcl-2 ratio, and decrease the expression of the invasiveness marker pS2 in ERα-positive breast cancer cells." (PMID 26580554, 2015). "VPA induces apoptosis through up-regulation of Bak and down-regulation of Bcl-2 genes expression in MCF7 breast cancer cells." (PMID 26580554, 2015). "COX-2+ TAMs promoted breast cancer cell proliferation and survival by increasing Bcl-2 and P-gp and decreasing Bax in cancer cells." (PMID 26359357, 2015). "That is why we observed isolated cases Bcl-2 positive breast cancer (weakly intense reaction) in cases of ER absence." (PMID 26112049, 2015). "Further analysis of its targets and upstream regulatory mechanism showed that highly expressed E2F7 represses miR-15a/16 expression, which then up-regulates Bcl-2 and Cyclin E1 to induce tamoxifen resistance of breast cancer cells." (PMID 26397135, 2015). "While Bcl-2 has emerged as an important prognostic marker in breast cancer, its precise role as a predictive marker or therapeutic target is not known." (PMID 26112049, 2015). "For this reason, we designed the siRNA mediated silencing of the Bcl-2 gene in the MCF-7 breast cancer cell line." (PMID 26535028, 2015). "High expression levels of BCL2 have also been shown to be a good predictor of late breast cancer recurrence in a subset of 73 patients with primary breast cancer." (PMID 25848913, 2015). "HIP1 is also overexpressed in several cancer tissues like breast cancer and possesses the oncogenic properties through BCL-2 and NF-κB pathways." (PMID 26296091, 2015). "Apoptosis was also induced in MDA-MB-231 breast cancer cells by EGCG (50 and 80 μM) associated with reduced Bcl-2 and Bax expression." (PMID 26694341, 2015). "Generation of the G-rich DNA aptamer AS1411, that targets nucleolin, has been proven effective in destabilising Bcl2 mRNA in MCF7 breast cancer cells." (PMID 25680182, 2015). "Consistent with our data, combined curcumin and emodin administration was shown to synergistically inhibit proliferation, survival and invasion of breast cancer cells where the antitumor effects were mediated through miR-34a by down regulating Bcl-2 and Bmi." (PMID 25786122, 2015). "Ubc9 has been shown to be a positive regulator of B-cell lymphoma 2 (Bcl-2) expression in breast cancer cell line MCF-7." (PMID 26416353, 2015). "Bcl-2 examination is expected to improve prediction of the clinical outcome or to predict response to Bcl-2-targeted therapy in breast cancer." (PMID 26472348, 2015).
breast carcinoma (continued). "Further, Bcl-2 expression frequently correlates with Estrogen Receptor (ER) expression levels in ER+ breast cancers." (PMID 25784482, 2015). "In order to gain insight into the mechanisms involved in apoptosis induction mediated by PNPC in breast cancer, we studied its effects on the expression of Bcl-2 and Bax proteins under in vivo situations." (PMID 25793208, 2015). "HER-2 blockade by herceptin is known to attenuate Bcl-2/Bcl-xl expression and push breast cancer cells towards apoptosis." (PMID 26156237, 2015). "The results presented here demonstrated that Nar-induced apoptosis relates to augmented levels of Bax and down-regulation of Bcl2 inducing mitochondrial dysfunction and leading to apoptosis of colorectal and breast cancer cells." (PMID 26074733, 2015). "In conclusion, our results indicated the possibility of complete down regulation of the Bcl-2 mRNA level by novel designed Bcl-2 in the MCF-7 human breast cancer cells." (PMID 26535028, 2015). "Using estrogen deprivation of ER+ human breast cancer cell lines as a model of AI treatment, one study showed that cell survival under these conditions is supported by increased activity of Bcl-2 at the mitochondria." (PMID 25784482, 2015). "In breast cancer cells, however, the anti-apoptotic protein BCL-2 was up-regulated, and both cell invasion and the proliferation rate were increased." (PMID 26219286, 2015). "In our study, we found that TAMs induced breast cancer cell survival by up-regulating Bcl-2 and p-gp and down-regulating Bax expression." (PMID 26359357, 2015). "The mRNA profiling analysis revealed that in the adjacent normal breast tissues compared to TN ones, oncogenic BCL2 is down-regulated whereas miR-21 in TN breast cancer tissues is over-expressed." (PMID 25705321, 2015). "And overexpression of miRNA-497 inhibited the survival of 4T1 breast cancer cells via targeting VEGFR2 and its downstream signal pathway proteins Bcl-2 and Bax expression, which markedly increased 4T1 breast cancer cells apoptosis." (PMID 26345385, 2015). "Their findings support the idea that Bcl-2 plays a crucial role in inhibition of breast cancer cells from autophagic cell death." (PMID 26535028, 2015). "Resveratrol and its analogue HS-1793 induced apoptosis in MCF-7 and MDA-MB-231 breast cancer cell lines by interfering with Bcl-2 gene expression." (PMID 26156237, 2015). "Previously we demonstrated that hsa-miR-195 targets BCL2, induces apoptosis and augmented the effect of etoposide in breast cancer cells." (PMID 26632252, 2015). "Ubc9 has been shown to regulate apoptosis as a positive regulator of Bcl-2 expression in breast cancer MCF-7 cells." (PMID 26416353, 2015). "Enhanced expression of Bcl-2 has been identified in other malignancies, including breast cancer, where its pathological function is less clear." (PMID 26091803, 2015). "The role of pro-apoptotic hsa-miR-195 in inhibiting de novo lipogenesis via targeting genes overexpressed in breast cancer (BCL-2, FASN, ACACA, HMGCR, CYP27B1) makes hsa-miR-195 an effective anticancer molecule." (PMID 26632252, 2015). "Trastuzumab-resistant HER2+ breast cancer cell lines frequently upregulate Bcl-2 and decrease Bax as a means of enhancing cell survival." (PMID 25784482, 2015). "Bcl-2 is frequently expressed in normal breast epithelial cells and breast cancer cells, and is known to be upregulated by estrogen." (PMID 26472348, 2015). "Patient-derived ER+ breast cancer xenografts treated with tamoxifen in combination with the Bcl-2/Bcl-xL/Bcl-w inhibitor ABT-737, an analogue of ABT-263, displayed decreased tumor growth and increased tumor cell death." (PMID 25784482, 2015). "In the context of breast cancers, Bcl-2 dysregulation promotes innate or acquired treatment resistance." (PMID 25784482, 2015). "Polycerasoidin induced mitochondrial-dependent apoptosis in breast cancer cells via caspase activation and changes in the mRNA and protein expression of Bax and Bcl-2." (PMID 25996383, 2015).
breast carcinoma (continued). "For example, Bcl-2 is overexpressed in about 85% of ER+ breast cancers, perhaps due to the fact that its promoter is directly bound and transactivated by ERα." (PMID 25784482, 2015). "In agreement with our results, previous work has shown that TIMP-4 regulates de expression of Bcl-2 proteins in a breast cancer mouse model." (PMID 26291714, 2015). "Overall results by western analysis showed increased Bcl-2, Oct-4 and Sox-2 expression with increased carboplatin concentration which demonstrates that these resistant breast cancer cells have characteristics of cancer stem cell behavior." (PMID 25837691, 2015). "Remarkably, miR-21 inhibition suppresses proliferation and migration of nasopharyngeal carcinoma and breast cancer cells through downregulation of anti-apoptotic BCL2." (PMID 26116372, 2015). "Over expression of Bcl-2 is frequently observed in several types of cancers and it is one of the prognostic markers in breast cancer." (PMID 26535028, 2015). "We have also shown that knockdown of GRP78, using RNAi in ER+ breast cancer cells, reduces overall cellular levels of anti-apoptotic BCL2, BCL-W, and BCL-xL." (PMID 26157705, 2015). "Although there is strong preliminary evidence supporting the roles of Bcl-2 and Bcl-xL in breast tumor formation and therapeutic resistance, high Bcl-2 protein levels in human breast cancer samples tend to correlate with a favorable prognosis." (PMID 25784482, 2015). "In the context of chemotherapy, clinical breast cancer specimens biopsied before and after a course of pre-operative neoadjuvant chemotherapy displayed increased Bcl-2 in residual post-treatment tumor cells." (PMID 25784482, 2015). "Bcl-xL has been shown to be more effective than Bcl-2 (approximately 10-fold) at inhibiting apoptosis in a cell culture model of breast cancer." (PMID 26187498, 2015). "The gene contributing majorly to the oncogenesis of breast cancer (survivin, stathmin and Bcl2) were significantly downregulated upon treating with chimeric construct." (PMID 26176230, 2015). "Bcl-2 expression in breast cancer has been reported to positively correlate with differentiated markers or favorable prognostic factors such as ER/PR expression, HER2 negativity, slow proliferation, small tumor size, and so on." (PMID 26472348, 2015). "We have previously reported that MCD potentiates the effect of Carb and 5-FU by reducing activation of Akt and decreasing Bcl-2 level in breast cancer cells." (PMID 25178635, 2014). "Bcl-2 is another regulator of apoptosis, but has been shown to be an important biomarker in male breast cancer pathogenesis, correlating with low mitotic cell count and smaller tumors with lower histological grade." (PMID 23755153, 2014). "β2-M and B-Cell Lymphoma/Leukemia 2 (Bcl-2) transcript expression levels in breast cancer tissue and the corresponding normal tissue were quantified using real-time PCR." (PMID 25292288, 2014). "In some studies Bcl-XL has been ~10 times more active than Bcl-2 in repressing apoptosis in breast cancer cell lines." (PMID 24864240, 2014). "Increased expression of the proapoptotic protein (Bax), along with reduced level of the antiapoptotic protein (Bcl-2), was observed in breast cancer MCF-7 cells after treatment with Lethariella zahlbruckneri extract." (PMID 25401123, 2014). "Our results showed that knockdown of EpCAM enhances the chemosensitivity of breast cancer cells to 5-FU by downregulating the expression of Bcl-2, suggesting EpCAM as a promising target for anti-cancer therapy." (PMID 25019346, 2014). "Immunoblot analysis was conducted to determine the expression of molecular markers for male breast cancer, including Bcl-2, caspase-3, survivin, and cyclin D1." (PMID 23755153, 2014).
breast carcinoma (continued). "Our results show that PTER-ITC induced apoptosis in breast cancer cells through caspase activation, which increased the Bax/Bcl-2 ratio and downregulated survivin." (PMID 25119466, 2014). "The aim of this retrospective study was to investigate the effect of B cell lymphoma 2 (BCL-2) expression on disease-free survival (DFS) in 172 early breast cancer (BC) patients treated with anthracycline-based adjuvant chemotherapy." (PMID 25005788, 2014). "TN breast cancer patients with BCL-2 overexpression had significantly higher DFS than those with BCL-2 negativity." (PMID 25005788, 2014). "The second exon of BCL-2 contains a CpG island and an ER-binding site, which helped to explain why the endocrine resistant breast cancer cells exhibit increased sensitivity to cytotoxic chemotherapy agents such as paclitaxel." (PMID 25606572, 2014). "For example, JMJD3 was suggested to regulate H3K27me3 levels at an enhancer element driving the expression of the BCL2 gene in breast cancer cells." (PMID 24797517, 2014). "Opposite findings were observed in adherent breast cancer cells exposed to microgravity: the Bcl-2 inhibitor of caspase activation increases, whereas proapoptotic effectors concomitantly decline." (PMID 25215287, 2014). "Previous data have shown that miR-21 targets Bcl-2 and participates in tumorigenesis of human glioblastoma, bladder cancer, and breast cancer." (PMID 25084400, 2014). "It was recently shown that MUC16 silencing in breast cancer cells is associated with up-regulation of TRAIL-R1 (DR4) and pro-apoptotic molecules Bid and Bax, and down-regulation of Bcl-2." (PMID 24690311, 2014). "The overexpression of miR-15a/16 can reduce the expression of the tamoxifen-induced BCL2, and enhance the resistance of breast cancer cells to tamoxifen." (PMID 25342041, 2014). "To confirm that TSA induced breast cancer cell apoptosis through the intrinsic pathway, we analyzed the expression of both anti-apoptotic (Bcl-2 and Bcl-xL) and pro-apoptotic (Bax) proteins by western blotting in the three cell lines." (PMID 24626188, 2014). "10058-F4 can decrease BCL2 protein levels; BCL2 and other anti-apoptotic BCL2 proteins confer antiestrogen resistance in breast cancer cells." (PMID 25339305, 2014). "To explore the significance of aberrant expression of p-ERK1/2 in TNBC for cancer targeted gene therapy of BikDD, we investigated the correlation between p-ERK1/2 expression and expression of Bik, Bcl-2, Bcl-Xl and Mcl-1 in 114 breast cancer patient samples." (PMID 24637719, 2014). "The aim of the present study was to evaluate the prognostic significance of BCL-2 expression in the group of 172 women with breast cancer in clinical stage T1–T2, N1–N2, M0, treated with ATC in adjuvant settings." (PMID 25005788, 2014). "Some studies have reported on the value of Bcl-2 expression as a good prognostic indicator in breast carcinoma." (PMID 25082024, 2014). "Immunohistochemistry markers of favorable prognosis of breast cancer include only ERα, PgR, Bcl-2 and E-cadherin." (PMID 24824621, 2014). "In various cancers, including breast cancer, colon cancer, and non-small cell lung cancer, Bcl-2 overexpression is a predicting factor of favorable clinical outcomes." (PMID 25332145, 2014). "Immunohistochemical staining for Bcl2 was performed on tissue microarrays of a total of 151 male breast cancer cases." (PMID 23573235, 2013). "Our data support Bcl-2 expression as a useful predictive factor for assessing treatment response to chemotherapy in breast cancer patients." (PMID 24370277, 2013).